SPARC (secreted protein acidic and cysteine rich)
Diseases named in the same sentence as SPARC in open-access papers (continued):
Sharing a sentence is not in itself a finding about the gene and the disease.
glioblastoma (20 papers, 2003 to 2025). The most malignant astrocytic tumor (WHO grade IV). "Finally, we linked IRE1α and AKT1 activity to SPARC production: PTEN-negative glioblastoma cells with high p-AKT1 levels produced SPARC when IRE1α was inactivated with the inhibitor 4μ8C." (PMID 31062076, 2019). "According to in vitro and in vivo studies, the results showed that the uptake of ICG-HSA complex was higher in SPARC-expressing glioblastoma cell line and tumor region compared with the uptake of free ICG." (PMID 36614294, 2023). "In conclusion, the ICG-HSA complex can be used as a NIR imaging agent for visualizing SPARC-expressing glioblastoma, which will be helpful for FGS." (PMID 36614294, 2023). "Here, we investigate the potential of the ICG-HSA complex as an imaging agent for visualizing SPARC-expressing glioblastoma by NIR imaging." (PMID 36614294, 2023). "Overall, we evaluated the potential of the ICG-HSA complex as a valuable fluorescence agent to improve FGS outcomes for glioblastoma patients by providing accurate resection of tumor margins via SPARC targeting of the tumor." (PMID 36614294, 2023). "Our results demonstrated that the ICG-HSA complex is likely to be used as an efficient imaging agent targeting SPARC-expressing tumors, especially glioblastoma." (PMID 36614294, 2023). "Previous studies have shown that SPARC regulates glioblastoma growth by altering the tumor microenvironment and inhibits tumor angiogenesis by inhibiting VEGF expression and secretion." (PMID 35721704, 2022). "In this study, we investigated the potential of HSA–CDDP as a therapeutic agent for a glioblastoma model and focused on the SPARC-mediated efficacy and safety." (PMID 33114661, 2020). "Glioblastoma cells seem to exploit the structural flexibility of Nogo-A-Δ20 using SPARC as a soluble decoy to attenuate the activation of inhibitory RhoA signaling via S1PR2." (PMID 31062076, 2019). "By analyzing infiltration into the corpus callosum, we provide in vivo evidence that glioblastoma cells require SPARC to invade white-matter structures." (PMID 31062076, 2019). "Reduced IRE1α activity enables glioblastoma cells with activated AKT signaling to secrete SPARC, which prevents an intrinsically disordered region of Nogo-A-Δ20 from further inducing RhoA signaling via S1PR2." (PMID 31062076, 2019). "Once translation is initiated, glioblastoma cells rapidly secrete SPARC to block Nogo-A from inhibiting migration via RhoA." (PMID 31062076, 2019). "Stress fiber formation in glioblastoma cells in response to RhoA activation induced SPARC which was prevented by interrupting actin assembly with latrunculin A (Lat-A)." (PMID 31062076, 2019). "SPARC expression has been observed not only in glioblastoma cells in the invasive zone but also in tumor cores with high cell density." (PMID 31062076, 2019). "We additionally performed immunohistochemical staining for SPARC in tissue sections of 26 IDH-wildtype glioblastomas [Suppl." (PMID 31062076, 2019). "We investigated the molecular mechanism by which glioblastoma cells produce SPARC in response to RhoA activation." (PMID 31062076, 2019). "We showed that glioblastoma cells with high p-AKT1/ENTPD5 levels produced SPARC in response to acute RhoA activation." (PMID 31062076, 2019). "In contrast to a study performed in a glioblastoma cell line, overall expression and secretion of TGFBI was unaffected by either loss or gain of SPARC in the Met5a cell line." (PMID 27622658, 2016). "For this reason, SPARC has been regarded as an enhancer of the capability of glioblastomas to localise in multiple sites of the brain." (PMID 16622457, 2006).
glioblastoma (continued). "To evaluate whether HSA–CDDP can be taken up by glioblastoma cells in a SPARC-mediated HSA-dependent manner, we performed cellular uptake imaging using confocal microscopy based on our previous paper." (PMID 33114661, 2020). "In these glioblastoma cells, SPARC localized to the ER (co-stained with calnexin; Suppl." (PMID 31062076, 2019). "However, this signaling disturbed the mRNA decay activity of IRE1α, thus enabling glioblastoma cells to increase the production of secreted glycoproteins such as SPARC." (PMID 31062076, 2019). "Together with the in vitro data, our UM invasion analysis demonstrated that increased AKT-driven ENTPD5 expression enabled glioblastoma cells to produce the Nogo-A decoy SPARC, which was key for their ability to invade the extensively myelinated corpus callosum." (PMID 31062076, 2019). "Consequently, blocking Nogo-A-Δ20 with recombinant SPARC prevented RhoA activation in glioblastoma cells [Suppl." (PMID 31062076, 2019). "In addition, TRAIL potently suppresses the expression of tissue remodelling factors, such as MMP-2 and TIMP-2, as well as of those promoting glioblastoma invasiveness, such as SPARC." (PMID 16622457, 2006). "Moreover, the expression of MMP-2, its inhibitor TIMP-2 and the tumour invasiveness-related protein SPARC were effectively inhibited by TRAIL in glioblastoma cell lines." (PMID 16622457, 2006). "Particularly, the expression of the following genes was affected in A172 cells after 24 h of treatment with TRAIL: VEGF, the MMP-2, the gene encoding TIMP-2, a protein regulating the activity of MMP-2 and SPARC, a protein involved in glioblastoma invasiveness processes." (PMID 16622457, 2006). "The protein SPARC has been regarded as a promoter of local invasiveness of glioblastoma." (PMID 16622457, 2006). "Additionally, the Scavenger Receptor Stabilin-1 (STAB1), identified as a receptor for the matricellular protein SPARC involved in glioblastoma cell migration, highlights its potential significance in cancer development and response to treatments like REGO, necessitating further exploration." (PMID 38534332, 2024). "Thus, the molecular mechanism we discovered may apply to both IDH-wildtype and IDH-mutant glioblastomas, influencing SPARC production via either IRE1α or AKT/ENTPD5 might represent a worthwhile therapeutic option to pursue." (PMID 31062076, 2019). "Furthermore, glioblastoma growth is marked by severe dysfunction of molecules such as the secreted protein acid rich in cysteine (SPARC), which, in normal cells, restraints invasiveness and is actually being regarded as a candidate main enhancer of high tissue invasiveness." (PMID 16622457, 2006). "The study evaluated two significantly upregulated genes, SPARC (secreted protein acidic and rich in cysteine) and VIM (vimentin) for glioblastoma." (PMID 35571016, 2022). "As a result, SPARC prevents Nogo-A from further activating S1PR2 and thus enables glioblastoma cells to invade white matter." (PMID 31062076, 2019). "In these studies, we observed high SPARC levels across all tumors, including PTEN-wildtype glioblastomas, both in cellular tumor areas and in less cellular areas of the infiltration zone." (PMID 31062076, 2019). "Glioblastoma cells have been shown to continuously produce high SPARC transcript levels; however, these levels do not correspond with the low SPARC protein level in cells without RhoA activation." (PMID 31062076, 2019). "Similarly, glioblastoma cells with low p-AKT1/ENTPD5, and thus low endogenous SPARC production, showed increased invasion through myelinated transwells in the presence of recombinant SPARC but not SPARC (del_Kazal)." (PMID 31062076, 2019).
glioblastoma (continued). "Notably, genes such as SPARC and VIM are upregulated in glioblastoma samples." (PMID 38840833, 2024). "Using a mouse model of glioblastoma, massive infiltration of CD68+ macrophages with bubbly cytoplasm and increased expression of phagocytic cell markers (glycogen, glycoproteins, glycolipids, and mucins) were detected in Sparc-null tumors indicating that SPARC promotes phagocytosis of tumor cells." (PMID 34209679, 2021). "Moreover, SPARC production occurred only when Nogo-A activated S1PR2 in trans, whereas overexpression of Nogo-A in glioblastoma cells did not induce SPARC [Suppl." (PMID 31062076, 2019). "Moreover, we confirmed this RhoA-mediated induction of SPARC in previously reported patient-derived glioblastoma cells which were cultured in the absence of serum, thus excluding serum-derived effects [Suppl." (PMID 31062076, 2019). "We further show that xenografted glioblastoma cells produced SPARC that both co-precipitated with Nogo-A and attenuated the binding of S1PR2, whereas deletion of the Kazal-like module prevented SPARC from co-precipitating with Nogo-A, thus rescuing S1PR2 binding [Suppl." (PMID 31062076, 2019).
non-small cell lung carcinoma (20 papers, 2010 to 2025). A group of at least three distinct histological types of lung cancer, including non-small cell squamous cell carcinoma, adenocarcinoma, and large cell carcinoma. "In the lung, SPARC that was found among the tumor-associated stroma of non-small cell lung cancer is correlated with poor prognosis." (PMID 35670884, 2022). "In non-small cell lung cancer, the localization (stromal or tumoral) of SPARC expression is associated with different disease prognosis." (PMID 30227835, 2018). "Interestingly, in pancreatic adenocarcinoma and non-small cell lung cancer, only SPARC expression in peritumoural stroma is associated with survival." (PMID 22321704, 2012). "These include SPARC, an extracellular glycoprotein that promotes metastasis in non-small-cell lung cancer, and MMP2 (matrix metalloproteinase 2), which is an activator of TGFβ and promotes cancer cell invasion by degrading type IV collagen." (PMID 39482615, 2024). "Investigations have shown that SPARC promotes pathological reactions in non-small-cell lung cancer (NSCLC) and idiopathic pulmonary fibrosis by encouraging microvascular remodeling and overproduction of ECM proteins." (PMID 37577749, 2023). "For example, SPARC-treated non-small-cell lung cancer cells CL1-5 and H1299 migrate more rapidly, and hevin, the closest SPARC family member, has exactly the opposite mode of action, since migration is enhanced in hevin-null primary dermal fibroblasts." (PMID 33321927, 2020). "In conclusion, these data suggest that WNK1 is a novel molecule in SPARC-mediated mesenchymal signaling pathway in non-small cell lung cancer." (PMID 28969021, 2017). "SPARC is essential for Snail-driven invasion through activation of mitogen-activated protein (MAP) kinase pathways in non-small cell lung cancer pathogenesis." (PMID 28969021, 2017). "Because Snail overexpression induces SPARC expression in non-small cell lung cancer, the role of Snail in SPARC-WNK1 signaling pathway was consequently evaluated." (PMID 28969021, 2017). "Treatment of SPARC increased cell proliferation, migration, and mesenchymal phenotype in two non-small cell lung cancer cell lines, CL1-5 and H1299." (PMID 28969021, 2017). "In patients with non-small cell lung cancer, higher SPARC expression and lower Kruppel-like factor 4 (KLF4) are detected in tumor tissue compared to non-tumor tissue." (PMID 28969021, 2017). "This study aims to investigate KLF4 and SPARC expression and their correlation with the clinical characteristics of non-small cell lung cancer (NSCLC)." (PMID 23249717, 2012). "Similarly, SPARC can be used to predict the response to nanoparticle-bound paclitaxel (nab-paclitaxel) in non-small cell lung cancer (NSCLC)." (PMID 34456964, 2021). "Besides, SPARC is a secreted matricellular protein governing cell adhesion, proliferation and differentiation, and driving pathological responses in non-small cell lung cancer." (PMID 31296175, 2019). "Moreover, genes associated with the migration of tumor cells such as SPARC, a glycoprotein associated with ECM, are involved in the development of non-small cell lung cancer." (PMID 29559981, 2018). "Our study suggests that blockage of SPARC/WNK1/Snail signaling pathway could be a strategy to suppress migration of non-small cell lung cancer." (PMID 28969021, 2017). "Both in non-small cell lung cancer (NSCLC) and IPF, SPARC is predominantly localized in migrating fibroblasts within fibroblastic foci and drives pathological responses by promoting ECM synthesis and turnover." (PMID 40970095, 2025). "Our results also show that SPARC treatment induces migration and EMT in highly metastatic non-small cell lung cancer cell lines CL1-5 and H1299." (PMID 28969021, 2017).
non-small cell lung carcinoma (continued). "In non-small cell lung cancer (NSCLC) cells, the extracellular matrix component secreted protein acidic and rich in cysteine (SPARC) promotes cell migration and epithelial to mesenchymal transition (EMT): SPARC induces AKT activation and increases WNK1 phosphorylation at T60." (PMID 30390653, 2018). "Snail, an important transcription factor of EMT program, induces SPARC expression in non-small cell lung cancer, but the SPARC-mediated signaling pathways are not fully understood." (PMID 28969021, 2017).
pulmonary fibrosis (18 papers, 2010 to 2025). Chronic progressive interstitial lung disorder characterized by the replacement of the lung tissue by connective tissue, leading to progressive dyspnea, respiratory failure, or right heart failure. "Our study also suggested an important role of the fibrogenic factor SPARC in COVID-associated lung fibrosis." (PMID 36405615, 2022). "Although SPARC was reported to be upregulated by TGF-β or angiotensin II in several types of fibroblast, it has not been fully elucidated whether other factors, associated with the progression of pulmonary fibrosis, upregulate SPARC expression." (PMID 23517551, 2013). "In systemic conditions such as lung fibrosis, skin fibrosis and pancreatic fibrosis, SPARC was shown to activate fibroblasts, increasing extracellular matrix production." (PMID 41375851, 2025). "As shown, with the use of 5-Aza-CdR, the expression of SPARC in pulmonary fibrosis cells was modulated." (PMID 40970095, 2025). "Emerging evidence has demonstrated that SPARC promotes excessive ECM protein deposition in idiopathic pulmonary fibrosis and keloid, as well as influences the proliferation and migration of fibroblasts." (PMID 40702440, 2025). "In our work, we sought to assess if aberrant methylation at the gene promoter region should be considered as one mechanism of SPARC dysregulation in lung fibrosis and if SPARC methylation correlates with IPF and/or NIPF." (PMID 40970095, 2025). "Among the top differentially expressed genes we found SPARC, LOXL1, and APP which have been implicated in lung fibrosis." (PMID 37085855, 2023). "We also showed that expression of SPARC in the lung was upregulated in the murine bleomycin-induced pulmonary fibrosis model, which was inhibited by TGF-β receptor I inhibitor." (PMID 23517551, 2013). "In the bleomycin-induced pulmonary fibrosis model, SPARC-null mice show a diminished amount of pulmonary fibrosis compared to controls." (PMID 23517551, 2013). "Recent studies suggested a significant contribution of SPARC to the pathogenesis of pulmonary fibrosis." (PMID 23517551, 2013). "In in vivo studies, C57BL/6 mice were induced for skin and lung fibrosis by bleomycin and followed by SPARC siRNA treatment through subcutaneous injection and intratracheal instillation, respectively." (PMID 20359365, 2010). "Conversely, the SPARC-null (SPARC−/−) mouse exhibited diminished bleomycin-induced pulmonary fibrosis in addition to other characteristics indicative of a compromised maturation and assembly of the ECM." (PMID 20195533, 2010). "Moreover, SPARC-null mice display a diminished degree of pulmonary fibrosis compared with control mice after exposure to bleomycin." (PMID 36405615, 2022). "Furthermore, fibronectin, OSM, and SPARC have been reported to participate in pathological situations such as tissue remodeling and pulmonary fibrosis in ARDS." (PMID 34130757, 2021). "In addition to its effects on TGF-β activation and signaling, SPARC also suppresses apoptosis of idiopathic pulmonary fibrosis fibroblasts through constitutive activation of β-catenin." (PMID 26656750, 2015). "Several mouse models have confirmed that SPARC is affiliated with pulmonary fibrosis." (PMID 25126876, 2014). "However, in patients with pulmonary fibrosis, the expression of SPARC was found to be increased and was localized to the cytoplasm of pulmonary fibroblasts." (PMID 25126876, 2014). "In addition, SPARC-null mice display a lesser amount of pulmonary fibrosis compared with wild type mice in animal models of bleomycin-induced pulmonary fibrosis." (PMID 25126876, 2014). "To investigate whether SPARC induction is also regulated by TGF-β in vivo, we studied SPARC gene expression in a bleomycin-induced murine pulmonary fibrosis model." (PMID 23517551, 2013).
pulmonary fibrosis (continued). "SPARC siRNA significantly reduced gene and protein expression of collagen type 1 in fibroblasts obtained from the TBR1CA; Cre-ER mouse that was induced for constitutively active TGF-β receptor I. Skin and lung fibrosis induced by bleomycin was markedly reduced by treatment with SPARC siRNA." (PMID 20359365, 2010). "Moreover, in animal studies, SPARC-null mice display a diminished amount of pulmonary fibrosis compared with control mice after exposure to bleomycin, a chemotherapeutic antibiotic with a profibrotic effect." (PMID 20359365, 2010). "Accumulating evidence suggests that SPARC may contribute to the progression of pulmonary fibrosis." (PMID 23517551, 2013). "Our research aimed to investigate SPARC promoter hypermethylation as a potential biomarker in patients affected by IPF and non-idiopathic pulmonary fibrosis (NIPF)." (PMID 40970095, 2025). "In the bleomycin-induced lung fibrosis model, blocking of TGF-β signaling by the ALK-5 inhibitor SB-525334 significantly decreased SPARC expression as well as the degree of fibrosis." (PMID 23517551, 2013). "In addition, SPARC expression is upregulated by TGF-β, which is thought to be a key regulator for the establishment and progression of IPF, not only in culture but also in the animal model of pulmonary fibrosis." (PMID 23517551, 2013).